C3 (complement C3)
Diseases named in the same sentence as C3 in open-access papers (continued):
Sharing a sentence is not in itself a finding about the gene and the disease.
glomerulonephritis (continued). "More specifically, early during experimental OV infection (8 weeks), hamsters develop a “mesangioproliferative glomerulonephritis”, characterized by the deposition of immune complexes (ICs) consisting of immunoglobulin (Ig) G, complement component 3 (C3), and OV tegumental antigen." (PMID 23717698, 2013). "The synthesis of monocyte C3 and other complement proteins could theoretically be important in the glomerular component of glomerulonephritis." (PMID 18836527, 2008). "Finally, a kidney biopsy was performed, which gave the result of C3-glomerulonephritis." (PMID 40149624, 2025). "C3 consumption and dysregulation of the complement system may also lead to defects in clearance of immune complexes, and autoimmune organ injury, particularly glomerulonephritis or (more rarely) vasculitis." (PMID 29696024, 2018). "Therefore, in any patient with a C3-dominant glomerulonephritis with features of post-infectious GN, persistent clinical abnormalities, including hypocomplementaemia, proteinuria or declining renal function, should lead to further investigation of the alternative pathway of complement." (PMID 28357053, 2017). "The nephrotoxic monoclonal IgM/kappa paraprotein seemed to trigger complement C3 activation and induced TMA with C3 glomerulonephritis." (PMID 41226350, 2025). "Anti-GBM antibodies at her initial presentation were positive at 72 U/ml, and her native kidney biopsy exhibited severe crescentic glomerulonephritis involving all 23 glomeruli and linear GBM immunofluorescence staining for IgG and complement C3 along the GBM." (PMID 33774048, 2021). "Moreover, the BMDCs-ALD-DNA induced mice displayed glomerulonephritis with hyperplasia in glomeruli and increased mesangial cells compared with control mice, the kidney from the model mice also appeared vasculitis with perivascular cell infiltration, glomerular deposition of IgG, and complement C3." (PMID 29321778, 2017). "This leads to excessive C3 deposition in the glomeruli, resulting in immunoglobulin-negative, C3-positive glomerulonephritis." (PMID 40342409, 2025). "The selective knockout of C3 and C4 in mouse models of anti-GBM-mediated glomerulonephritis demonstrated the involvement of both the alternative and classical pathways in pathogenesis, with less glomerular neutrophil infiltration and lower proteinuria values, relative to wild-type mice." (PMID 37475859, 2023). "This leads to glomerular deposits of complements without significant immunoglobulin deposits, thus leading to an immunoglobulin-negative C3 positive glomerulonephritis (C3 glomerulopathy)." (PMID 28210641, 2017). "Glomerulonephritis due solely to alternative pathway activation would be expected to show C3 in glomeruli on immunofluorescence with no immunoglobulins, C1q or C4." (PMID 28357053, 2017). "The glomerulonephritis associated with monoclonal gammopathy generally reveals MPGN by LM and C3 deposition with or without immunoglobulins by IF." (PMID 27878657, 2017). "It is not uncommon that typical cases of postinfectious glomerulonephritis show deposition of C3 without immunoglobulin." (PMID 25506445, 2014). "Screening tests for glomerulonephritis revealed a low C3 and negative ANA, ASO, DNAse-B, and ANCA." (PMID 28210641, 2017). "C3 glomerulonephritis is recognized by the presence of glomerulonephritis under light microscopy, immunofluorescent staining with C3, but not with immunoglobulins, C4 or C1q, and the presence of mesangial or subendothelial deposition, which can be observed using electron microscopy." (PMID 27460033, 2016). "Glomerulonephritis with dominant C3 deposition in our patient could not rule out C3 glomerulonephritis at the time of renal biopsy based on C3 glomerulopathy: consensus report." (PMID 25506445, 2014). "We detected glomerular FHR5, C3, and C5b-9 in 2 cases of CFHR5 nephropathy, 1 with and 1 without glomerular inflammation and clinical signs of glomerulonephritis." (PMID 31701048, 2019).
C3 glomerulopathy (85 papers, 2012 to 2026). "Taken together, the FHR51-9FH1-5 protein reduced glomerular C3 in experimental models of C3 glomerulopathy driven by either FH deficiency or mutated FHR5." (PMID 41810513, 2026). "C3 glomerulopathies are characterized by dominant C3 deposition in the glomeruli and are often associated with persistent low C3 levels, proteinuria, hematuria, and progressive renal impairment." (PMID 40995257, 2025). "C3 Glomerulopathy (C3G) is a complement-mediated disease, with predominant C3 deposits, where pathogenic genetic variants in complement system components and circulating autoantibodies result in loss of control of the alternative pathway, have been described." (PMID 39497737, 2024). "It was demonstrated that C3 glomerulopathy is associated with elevated levels of urinary complement proteins (C3, C4, FB, properdin, and C5) and complement activation products (C3a, Ba, Bb, C5a, and soluble C5b-9)." (PMID 38895123, 2024). "For example, mutations that cause a complete Factor H deficiency lead to uncontrolled complement activation in the fluid phase and are linked to C3 glomerulopathy (C3G), a heterogeneous histopathological entity characterized by glomerular C3 deposition." (PMID 34682837, 2021). "FH binds to C3b and the association between abnormal FHR-5 proteins and C3 glomerulopathy has been proposed to be due to an ability of FHR-5 to out-compete FH for interaction with C3b." (PMID 34193601, 2021). "Factor H-deficient (Cfh-/-) mice develop C3 glomerulopathy together with a reduction in plasma C3 levels." (PMID 33129896, 2021). "Known autoimmune causes of C3 glomerulopathy include autoantibodies that target either single complement proteins or protein complexes (the C3 and the C5 convertase)." (PMID 34613485, 2021). "FH-deficient mice, mimicking C3 glomerulopathy, have been treated with human plasma-derived FH, resulting in a reduction in complement activity and C3 deposition on the glomerular basement membrane." (PMID 33362763, 2020). "In C3 glomerulopathy caused by defective FH, for example, C3 is depleted systemically through uncontrolled AP activation." (PMID 32062771, 2020). "Genetic causes of C3 glomerulopathy include mutations in the genes coding for Factor H, C3, CFHR1, CFHR2, CFHR3, CFHR5, and Factor B. Factor H gene mutations are mostly homozygous or compound heterozygous." (PMID 31611870, 2019). "Autoantibodies can bind to components and complexes and alter function; for example, nephritic factors can stabilise the C3 and C5 convertases and are associated with diseases such as C3 glomerulopathy (C3G) and acquired partial lipodystrophy (APL)." (PMID 28986638, 2018). "Another, slightly extended construct containing CCP1–5 and 18–20 domains effectively inhibited complement activation in vivo and reduced abnormal glomerular C3 deposition in a FH-deficient mouse model of C3 glomerulopathy." (PMID 30135690, 2018). "The commonest acquired factors associated with C3 glomerulopathy are C3 nephritic factors (C3nefs), which are autoantibodies that bind to and stabilise the alternative pathway C3 convertase by preventing its inactivation by factor H44." (PMID 28357053, 2017). "Similarly, mutations in the Factor H, FHR1, FHR3, FHR5, and C3 genes are described in two or more diseases, such as C3 glomerulopathy, genetic HUS, IgA nephropathy, and AMD." (PMID 34613485, 2021). "C3 glomerulopathy is a recently defined entity that encompasses a group of kidney diseases caused by abnormal control of complement activation with deposition of complement component C3 in glomeruli leading to variable glomerular inflammation." (PMID 28357053, 2017). "Acquired causes of C3 glomerulopathy include antibodies affecting AP inhibition, such as anti-complement factor H or factor I, or those stabilising the activation of C3 convertase, such as C3 nephritic factor (C3Nef)." (PMID 25380644, 2014).
C3 glomerulopathy (continued). "Thus, renin/C3 correlations would be skewed due to pharmacological intervention thereby increasing renin, and the presence of nephritic factors or genetic variants in C3 glomerulopathy, which would lower C3 levels." (PMID 40242769, 2025). "Complement 3 glomerulopathy (C3G), an ultra-rare chronic kidney disease, is associated with dysregulation of the complement alternative pathway (AP) in plasma and the glomerular microenvironment, thereby resulting in accumulation of C3 and its split products in the glomerulus." (PMID 39110227, 2024). "Also, C3 and Factor B gene mutations are reported in C3 glomerulopathy." (PMID 34613485, 2021). "C3 glomerulopathy (C3G) is a clinicopathologic entity characterized by glomerular inflammation with dominant staining for C3 on immunofluorescence microscopy." (PMID 42284585, 2026). "The role of C5 is also being studied in C3 glomerulopathy, a rare disease of the kidney in which acquired autoantibodies target the C3 or C5 convertases, dysregulating complement activation." (PMID 41189475, 2025). "To assess the in vivo role of TSP-1 in the absence of FH, we used FH-deficient mice, an established model for complement overactivation, characterized by low serum C3 levels and extensive C3 deposition within the kidneys, resembling C3 glomerulopathy." (PMID 40338657, 2025). "In humans, C3 glomerulopathy is characterized by C3 deposits and the dysregulation of alternative complement pathways." (PMID 39940240, 2025). "The differential diagnosis of isolated C3 staining mainly includes C3 glomerulopathy and post-infectious glomerulonephritis (PIGN)." (PMID 40342409, 2025). "C3 glomerulopathy (C3G) is a rare form of glomerular disease characterized by C3 deposition on kidney biopsy." (PMID 40453077, 2025). "Among the broad spectrum of membranoproliferative glomerulonephritis (MPGN), immunofluorescence distinguishes C3 glomerulopathy (C3G), with predominant C3 deposits, and immunoglobulin-associated MPGN (Ig-MPGN), with combined C3 and Ig." (PMID 37604793, 2024). "Hyperactivation of the alternative complement pathway with involvement of CFB results in the development of C3 glomerulopathy, which leads to accumulation of the C3 component and glomerular injury." (PMID 39896931, 2024). "C3 glomerulopathy is a rare disease, characterized by an abnormal activation of the complement's alternative pathway that leads to the accumulation of the C3 component in the kidney." (PMID 38928213, 2024). "Detailed characteristics of all patients with posttransplant C3 glomerulopathy (reference for serum C3 levels: 90–180 mg/dL)." (PMID 39021814, 2024). "Dysregulation of the complement pathway—by genetic defects, mainly related to CFH or by autoimmune diseases, mainly related to autoantibodies (such as C3, C4, and C5 nephritic factors) against components of the pathway—results in C3 glomerulopathy." (PMID 39780910, 2024). "The histopathologic features of C3 glomerulopathy are characterized by deposition of C3, the absence or minimal immunoglobulin deposition within the glomeruli, evidence of glomerular inflammation, and mesangial cell proliferation." (PMID 39534179, 2024). "C3-glomerulopathy (C3G) is a rare pediatric kidney disease characterised by dysregulation of the alternative complement pathway, with glomerular deposition of C3." (PMID 37493956, 2024). "Cases in which the sole or dominant immunoreagent in the renal tissue is C3 or C4 are classified as primary GN and are defined as C3 glomerulopathy or C4 glomerulopathy." (PMID 38076230, 2023). "For that, C3 glomerulopathy (C3G) should be diagnosed if C3 deposition is clearly dominant over immunoglobulins." (PMID 35693785, 2022). "Now, C3 intervention is emerging as a viable therapeutic strategy for rare inflammatory kidney diseases, such as C3 glomerulopathy." (PMID 35874697, 2022).
C3 glomerulopathy (continued). "Since the re-classification of membranoproliferative glomerulonephritis the new disease entity C3 glomerulopathy is diagnosed if C3 deposition is clearly dominant over immunoglobulins in immunohistochemistry or immunofluorescence." (PMID 35693785, 2022). "C3 glomerulopathy (C3G) is a rare kidney disorder characterized by predominant glomerular depositions of complement C3." (PMID 34476601, 2022). "Standard diagnosis of C3 glomerulopathy is made by evaluating a kidney biopsy for intense C3 staining, substantially higher (two orders of magnitude) as immunoglobulin staining." (PMID 34613485, 2021). "Genetic causes of C3 glomerulopathy have been reported and single complement genes, including the Factor H, FHR1, FHR2, FHR3, FHR4, FHR5, and the C3 gene." (PMID 34613485, 2021). "Variations in the genes Factor H, FHR1, FHR3, and C3 are reported in both C3 glomerulopathy and in HUS." (PMID 34613485, 2021). "A common characteristic of C3 glomerulopathies (C3G) is C3 fragment deposition in the renal tissue leading to irreversible kidney damage." (PMID 33671302, 2021). "C3 Glomerulopathy (C3G) is diagnosed in cases with dominant C3 staining at least two orders of magnitude greater than any other immunoreactant." (PMID 34211499, 2021). "Complement activation, leading to generation and subendothelial deposition of complement split products in cases of C3 glomerulopathy, mostly leads to the influx of macrophages and neutrophils, likely attracted by C3a and C5a." (PMID 34613485, 2021). "C3 glomerulopathy (C3GP) is a disease entity caused by abnormality of the complement alternative pathway (AP) and characterized by C3 deposition in glomeruli." (PMID 34149444, 2021). "Autoimmune factors in C3 glomerulopathy include C3-Nef (C3-nephritic factor) which are autoantibodies that bind to neoepitopes of the assembled AP C3 convertase." (PMID 34613485, 2021). "Although the truncated model simulates the depletion of C3 as observed clinically in a few cases of C3 glomerulopathy, in chronic CS diseases the physiological response is likely to be less severe." (PMID 32062771, 2020). "The activation response is acute and can lead to complete depletion of C3 as informed by clinical observations (e.g. C3 glomerulopathy)." (PMID 32062771, 2020). "C3 glomerulopathy (C3G) is characterized by predominant glomerular C3 fragment deposition with electron-dense deposits on electron microscopy." (PMID 31823738, 2019). "C3 glomerulopathy (C3G) is an umbrella classification for severe renal diseases characterized by predominant staining for complement component C3 in the glomeruli." (PMID 31263464, 2019). "C3 glomerulopathy (C3G) is a recently introduced classification for rare but severe renal diseases characterized by predominant deposition of complement component C3 in glomeruli." (PMID 31263464, 2019). "Autoimmune factors in C3 glomerulopathy include autoantibodies in form of C3-Nephritic Factor, C4-Nephritic Factor or C5-Nephritic Factor." (PMID 31611870, 2019). "This process is believed to be driven via the dysregulation of alternative complement pathway and consequently, glomerular deposition of monoclonal immunoglobulins or C3 immune complexes, resulting in C3 glomerulopathy." (PMID 28210641, 2017). "In many cases of C3 glomerulopathy, the deposition of C3 in glomeruli leads to subsequent activation of C5 and there is considerable interest in the possibility of using the anti-C5 antibody eculizumab for treatment." (PMID 28357053, 2017). "A new definition of C3 glomerulopathy was therefore proposed when C3 dominance is at least two orders of magnitude stronger than any other immune reactant." (PMID 27717365, 2016). "Predominant C3 deposits detected by immunofluorescence define C3 glomerulopathy but its original definition as “C3 only” appeared too stringent if the goal of the diagnosis is to identify all candidates for evaluation of complement AP dysregulation." (PMID 27717365, 2016).
C3 glomerulopathy (continued). "Mice with deficiency of factor H (Cfh–/–), a negative alternative pathway regulator, are an established experimental model of C3 glomerulopathy in which complement C3 fragments including iC3b accumulate along the glomerular basement membrane." (PMID 26924054, 2016). "C3 glomerulopathies are rare chronic kidney diseases, characterized by predominant C3 deposits in glomeruli, in particular, in the mesangium and along the glomerular basement membrane, frequently associated with mesangial cells proliferation." (PMID 26074922, 2015). "C3 glomerulopathy (G3GP) is a term coined for glomerular diseases characterized by accumulation of complement C3 with absence or trace amount of immunoglobulin deposition in the glomeruli." (PMID 25889427, 2015). "The presence of predominant or isolated C3 accumulation suggests activation of the alternative pathway (AP) of complement, and many cases of C3 glomerulopathy show genetic or acquired AP dysregulation." (PMID 24161036, 2013). "C3 glomerulopathy refers to those renal lesions characterized histologically by predominant C3 accumulation within the glomerulus, and pathogenetically by aberrant regulation of the alternative pathway of complement." (PMID 24161036, 2013). "Kidney biopsy 1 year after presentation showed isolated glomerular complement C3 deposition, membranoproliferative changes, and subendothelial, intramembranous and occasional subepithelial electron-dense deposits consistent with C3 glomerulopathy." (PMID 22503529, 2012). "Anti-factor B antibody may help to determine the indication of kidney biopsy in case of nephritic syndrome with low C3 levels, helping to prevent the misdiagnosis of C3 glomerulopathy." (PMID 41246678, 2025). "In this case, C3 bright staining suggested C3 glomerulopathy." (PMID 41333025, 2025). "C3 glomerulopathy cannot be excluded, and follow-up on complement C3 levels is recommended." (PMID 40342409, 2025). "C3 glomerulopathy (C3G) is a complement-mediated disease, with predominant C3 deposits." (PMID 39497737, 2024). "C3 glomerulopathy is characterized by dominant C3 deposits with a membranoproliferative pattern." (PMID 39133392, 2024). "However, the presence of C3 alone has been considered insufficient to define C3 glomerulopathy, and a proposed definition requires C3 dominant and at least two orders of magnitude more intense than any other immune reactant." (PMID 38076230, 2023). "This may be due to the strict selection criteria, as we excluded cases with sole deposition of C3 to exclude cases of C3 glomerulopathy (C3G) presenting after an episode of infection." (PMID 36211394, 2022). "The strong C3 staining with IgA co-dominance and low serum C3 level at presentation suggest dysregulated activation of the complement system as is seen with C3 glomerulopathy (C3G) or IC-MPGN, and can act as a disease-modifying factor in IgA nephropathy or IgA vasculitis." (PMID 35757129, 2022). "Additionally, the FDA recently approved Pegcetacoplan, a C3 inhibitor, for paroxysmal nocturnal hematuria and phase II trials are currently ongoing regarding use in kidney transplant recipients with recurrent C3 glomerulopathy (NCT04572854)." (PMID 36311730, 2022). "More recently, MPGN has been reclassified into two diseases: immune-complex MPGN (IC-MPGN) and C3 glomerulopathy (C3G) based on immunofluorescence findings in kidney biopsies: predominant or exclusive C3 deposits in C3G and combined immunoglobulins and complement deposits in IC-MPGN." (PMID 34520493, 2021). "C3 glomerulopathy is characterized by accumulation of complement C3 within glomeruli." (PMID 33129896, 2021). "The rare glomerulopathy caused by the defective regulation of the alternative complement pathway and characterized by C3 deposition in the glomeruli (detected by immunofluorescence) in the absence of immunoglobulin/immune complexes has been defined as C3 glomerulopathy." (PMID 34064132, 2021).